HNRNPU (heterogeneous nuclear ribonucleoprotein U)
Diseases named in the same sentence as HNRNPU in open-access papers (continued):
Sharing a sentence is not in itself a finding about the gene and the disease.
allergic asthma (1 paper, 2020). A asthma with a basis in a pathological type I hypersensitivity reaction. "Adult allergic and non-allergic asthma differed in the expression of three lncRNAs from each other, RP11-325K4.3, HNRNPU and OIP5-AS1 expressed higher in allergic asthma." (PMID 33168013, 2020). "RP11-325K4.3, HNRNPU and OIP5-AS1 expressed higher in allergic asthma than in non-allergic asthma." (PMID 33168013, 2020).
asthma (1 paper, 2020). "In our measurements, HNRNPU showed increased expression in severe asthma compared with mild asthma, while OIP5-AS1 showed increased expression in COPD compared to asthma." (PMID 33168013, 2020).
bladder tumors (1 paper, 2022). "Finally, we analyzed the expression of HNRNPU in the immune cells of bladder tumor tissues." (PMID 35130920, 2022).
bladder urothelial carcinoma (1 paper, 2022). "Our study demonstrated that HNRNPU expression is associated with cisplatin sensitivity in bladder urothelial carcinoma cells." (PMID 35130920, 2022).
breast tumour (1 paper, 2022). "In addition, we examined HNRNPU expression using six pairs of tumour and adjacent normal tissues, and the results showed that HNRNPU levels were elevated in breast tumour tissues." (PMID 36347834, 2022).
colon adenocarcinoma (1 paper, 2025). "In this study, we found that HnRNPU expression was upregulated in colon adenocarcinoma (COAD) tissues compared with normal colon tissues and is correlated with poor prognosis." (PMID 41310105, 2025).
colorectal adenocarcinoma (1 paper, 2022). The most common type of colorectal carcinoma. "Collectively, high expressions of hnRNPA1, hnRNPK, hnRNPR, and hnRNPU were significantly associated with better OS rates for colorectal adenocarcinoma patients." (PMID 35875075, 2022). "Furthermore, we demonstrated that high expressions of hnRNPA1, hnRNPK, hnRNPR, and hnRNPU were associated with better overall survival rates for colorectal adenocarcinoma patients." (PMID 35875075, 2022). "In the present study, we discovered that the expression of hnRNPU in colorectal adenocarcinoma was increased, while the DNA methylation level of hnRNPU was decreased." (PMID 35875075, 2022). "The results showed that hnRNPA1, hnRNPK, hnRNPR, and hnRNPU in the nucleus had higher expressions in colorectal adenocarcinoma cells compared with FHC cells." (PMID 35875075, 2022). "Immunohistochemical staining revealed that hnRNPA1, hnRNPA2B1, hnRNPC, hnRNPK, hnRNPR, and hnRNPU are overexpressed in colorectal adenocarcinoma." (PMID 35875075, 2022). "By using IHC staining of 10 human colorectal adenocarcinoma specimens, we confirmed that hnRNPA1, hnRNPA2B1, hnRNPC, hnRNPK, hnRNPR, and hnRNPU were mainly localized in the nucleus and had higher expressions in colorectal adenocarcinoma tissues compared with adjacent normal tissues (ANT)." (PMID 35875075, 2022). "But until now, the expression and role of hnRNPU in colorectal adenocarcinoma has been unclear." (PMID 35875075, 2022).
depression (1 paper, 2024). "Then, we confirmed the function of circ-UBE2K and the specific mechanism by which it binds to the HNRNPU protein to regulate UBE2K protein expression and mediate abnormal microglial activation to promote the development of depression." (PMID 38994030, 2024). "Mechanistically, we found that circ-UBE2K interacts with the HNRNPU protein to regulate UBE2K protein expression, mediate abnormal microglial activation, and promote the progression of depression." (PMID 38994030, 2024).
diabetes (1 paper, 2020). "Among these are genes associated with insulin (MAX, NUCKS1, PIK3R1, PTPN11), diabetes (PIK3R1) and circadian-related processes (HNRNPU, BHLHE41)." (PMID 34745571, 2020).
early-onset epilepsy (1 paper, 2017). "All six patients with constitutive de novo HNRNPU mutations had early-onset epilepsy." (PMID 28283832, 2017).
endometrial cancer (1 paper, 2025). Primary or metastatic malignant neoplasm involving the endometrium (mucous membrane that lines the endometrial cavity). "Some DNA-binding proteins such as heterogeneous nuclear ribonucleoprotein L (HNRNPL), heterogeneous nuclear ribonucleoprotein U (HNRPU), and interleukin enhancer binding factor 2 (ILF2) are closely associated with endometrial cancer." (PMID 40575382, 2025).
esophageal cancer (1 paper, 2025). A primary or metastatic malignant neoplasm involving the esophagus. "Our analysis revealed significantly elevated hnRNPU expression in neoplastic tissues compared to adjacent normal tissues in gastric, colorectal, lung, and esophageal cancers." (PMID 39773744, 2025).
female infertility (1 paper, 2026). Diminished or absent ability of a female to achieve conception. "Loss of hnRNPU in oocytes disrupts this bidirectional signaling, impairs GC function, induces follicular apoptosis, and ultimately leads to defective folliculogenesis and female infertility." (PMID 41524182, 2026). "Taken together, our findings underscore the important role of hnRNPU in maintaining mitochondrial function and oocyte competence, thereby deepening our understanding of the molecular mechanisms contributing to female infertility." (PMID 41524182, 2026).
glioma (1 paper, 2023). A benign or malignant brain and spinal cord tumor that arises from glial cells (astrocytes, oligodendrocytes, ependymal cells). "By understanding the involvement of DKC1 and HNRNPU in the context of glioma biology, researchers may gain valuable insights into the underlying mechanisms of glioma pathogenesis." (PMID 37593751, 2023).
holoprosencephaly (1 paper, 2023). Holoprosencephaly (HPE) is a complex brain malformation resulting from incomplete cleavage of the prosencephalon, occurring between the 18th and 28th day of gestation, and affecting both the forebrain and face, which results in neurological manifestations and facial anomalies of variable severity. "Patients with HNRNPU mutations present with a variety of central nervous system abnormalities, including neuronal migration defects, enlarged lateral ventricles, corpus callosum defects, delayed myelination and mild holoprosencephaly." (PMID 37782669, 2023).
Hyperglycemia (1 paper, 2025). An increased concentration of glucose in the blood. "Hyperglycemia induces aberrant expression of long non-coding RNAs (e.g., lncRNA evf-2) in podocytes, which bind heterogeneous nuclear ribonucleoprotein U (hnRNPU) to regulate cell cycle re-entry and inflammatory responses, exacerbating podocyte detachment." (PMID 40641971, 2025).
Infertility (1 paper, 2026). "These mitochondrial phenotypes closely resemble those observed in aged oocytes, thus highlighting that dysregulation of hnRNPU may accelerate ovarian aging, ultimately leading to infertility." (PMID 41524182, 2026). "Furthermore, we demonstrated that hnRNPU deletion disrupts oocyte‐granulosa cell communication and induces granulosa cell apoptosis, but the precise molecular mechanisms linking these defects to impaired folliculogenesis and infertility remain to be clarified." (PMID 41524182, 2026).
kidney damage (1 paper, 2021). "The other six markers, CDC5L, HNRNPU, NUDT21, PAPOLA, POLR2B, and WBP4, were all negatively correlated with GFR, indicating that these genes may aggravate kidney damage in patients with LN." (PMID 34557492, 2021).
laryngeal squamous cell carcinoma (1 paper, 2026). A squamous cell carcinoma that arises from the larynx. "Furthermore, the lncRNA surfactant-associated 1 pseudogene (SFTA1P) has been demonstrated to enhance cisplatin-induced apoptosis by modulating the heterogeneous nuclear ribonucleoprotein U (hnRNP-U)-DNA damage-inducible protein GADD45 alpha (GADD45A) pathway in laryngeal squamous cell carcinoma." (PMID 41362671, 2026).
latent infection (1 paper, 2021). "In view of the fact that HNRNPU associates with LANASIM, we attempted to examine whether HNRNPU undergoes SUMOylation in response to KSHV latent infection and hypoxia." (PMID 34726485, 2021). "The SUMOylation of HNRNPU is enhanced by KSHV latent infection and responds to hypoxia." (PMID 34726485, 2021). "To further determine the role of HNRNPU in KSHV latently infected cells and in response to hypoxia, we performed immunofluorescence assays to examine the localization of HNRNPU in the iSLK cell line and its derived iSLK.219 cells with KSHV latent infection under normoxia or hypoxia conditions." (PMID 34726485, 2021). "Further investigation revealed that SUMOylation of HNRNPU is greatly enhanced by KSHV latent infection, while only the SUMO2/3- and not the SUMO1-modified form of HNRNPU induced by KSHV responds to hypoxia." (PMID 34726485, 2021).
male infertility (1 paper, 2021). The inability of the male to effect fertilization of an ovum after a specified period of unprotected intercourse. "The loss of function of hnRNPU in mouse Sertoli cells causes complete male infertility, characterized by severe testicular atrophy, rapid depletion of both Sertoli cells and germ cells, aberrant spermatogonia development and migration during pre-pubertal testicular development." (PMID 34815802, 2021).
monoclonal gammopathy of undetermined significance (1 paper, 2022). "HNRNPU mRNA was significantly increased in MM cells compared with NP cells and monoclonal gammopathy of undetermined significance (MGUS) cells." (PMID 35260179, 2022).
oral cancer (1 paper, 2015). "In this respect, we observed other members of the hnRNP family including hnRNPA2/B1, hnRNPK, hnRNPU, hnRNPG forming heterodimers with hnRNPD in oral cancer cells." (PMID 26318153, 2015).
polymicrogyria (1 paper, 2019). A developmental brain abnormality characterized by an excessive amount of small convolutions on the surface of the brain and cognitive dysfunction. "The patient carrying a large (>100 Mb) duplication involving, among many other genes, HNRNPU and AKT3, had a complex phenotype including neonatal seizure onset, polymicrogyria, and multiple cardiac defects." (PMID 30866059, 2019).
schizophrenia (1 paper, 2019). A major psychotic disorder characterized by abnormalities in the perception or expression of reality. "We also found altered levels of hnRNPC, hnRNPK and hnRNPU in post mortem samples of the anterior temporal lobe (ATL) from patients with schizophrenia." (PMID 30890939, 2019).
Seizure (1 paper, 2020). A seizure is an intermittent abnormality of nervous system physiology characterized by a transient occurrence of signs and/or symptoms due to abnormal excessive or synchronous neuronal activity in the brain. "Two out of four patients with febrile seizures in our cohort had a gene variant, such as HNRNPU, or a microdeletion at Xp22.31." (PMID 32913952, 2020).
temporal lobe epilepsy (1 paper, 2023). A localization-related (focal) form of epilepsy characterized by recurrent seizures that arise from foci within the temporal lobe, most commonly from its mesial aspect. "While the location of seizure onset was not reported for most individuals with HNRNPU mutations, two patients reportedly had temporal lobe epilepsy." (PMID 37782669, 2023).
cancer (35 papers, 2007 to 2025). A tumor composed of atypical neoplastic, often pleomorphic cells that invade other tissues. "Elevated HnRNPU expression has been implicated in cancer progression and is associated with poor prognosis." (PMID 41310105, 2025). "Aberrant expression and dysregulation of HNRNPU have been implicated in various human diseases, including cancers and neurological disorders." (PMID 37407733, 2023). "Down-regulation of HNRNPU expression led to inhibition of cell proliferation and was associated with good prognosis in cancer patients." (PMID 35130920, 2022). "HNRNPU was found to be implicated in several processes, including regulation of the innate immunity, proliferation and several diseases like cancers and eosinophilic asthma." (PMID 33168013, 2020). "Abnormal expression of HnRNPU has been associated with cancer initiation and progression." (PMID 41310105, 2025). "Moreover, high hnRNPU expression was significantly associated with poor prognosis, consistent with observations in other human cancers." (PMID 39773744, 2025). "The results demonstrated significant upregulation of HnRNPU in various cancer types, including BRCA, CHOL, COAD and ESCA." (PMID 41310105, 2025). "While previous studies have shown the role of specific hnRNPs, such as hnRNPU, in other cancers, the functional impact of hnRNPU in GC remain unexplored, making it a potential target for AS regulation in this disease." (PMID 39773744, 2025). "In this study, we identified an alternative splicing signature associated with the acquisition of malignant phenotypes in various types of cancer, and further elucidated hnRNPU as a key splicing factor dysregulated in GC." (PMID 39773744, 2025). "In T24 cancer cells with high HNRNPU expression, the knockout of HNRNPU inhibited cell proliferation, invasion, and migration." (PMID 40361412, 2025). "To elucidate the role of hnRNPU in cancer progression, we analyzed hnRNPU expression levels across various cancer types using TCGA database." (PMID 39773744, 2025). "Northern blot assay using a junction-specific probe indicated the existence of 597-nt circ-hnRNPU in a variety of cancer cell lines, and those stably transfected with empty vector (mock) or circ-hnRNPU." (PMID 37993881, 2023). "Based on lower and upper quartiles, the circ-hnRNPU levels in cancer cells were classified into relatively low, medium and high abundance." (PMID 37993881, 2023). "In therapeutic experiments on cancer metastasis, intravenous administration of lentivirus carrying circ-hnRNPU decreased the lung metastatic colonies and increased the survival probability of nude mice treated with tail vein injection of MKN-45 cells." (PMID 37993881, 2023). "Further research is needed to explore the comprehensive role of FAM171B and its interaction with HNRNPU in cancer." (PMID 37915048, 2023). "Exploration of other protein partners is helpful for elucidating additional functions of circ-hnRNPU during cancer progression." (PMID 37993881, 2023). "In cancer progression, an hnRNPU axis regulated chromatin looping, cell apoptosis, and chemotherapy response." (PMID 35875075, 2022). "Currently, eight hnRNPs members (hnRNPA1, hnRNPA2B1, hnRNPC, hnRNPD, hnRNPF, hnRNPK, hnRNPR, and hnRNPU) seem to be more relevant to cancer development, according to reported literature." (PMID 35875075, 2022). "We performed genome-wide CRISPR screening in T24 cancer cells in vitro, and identified that the gene heterogeneous nuclear ribonucleoprotein U (HNRNPU) was the top candidate gene related to cisplatin resistance." (PMID 35130920, 2022). "In the high HNRNPU expressing T24 cancer cells, knockout of HNRNPU inhibited cell proliferation, invasion, and migration." (PMID 35130920, 2022). "Previously, HNRNPU has been reported to facilitate chromatin looping and p300‐mediated transactivation of transcription factor early growth response 1, thus promoting cancer progression." (PMID 32915499, 2020).
cancer (continued). "For example, HPSE eRNA promotes cancer progression by interfering with the chromatin looping and regulating the hnRNPU/p300/EGR1/HPSE axis." (PMID 33392092, 2020). "The effects of hnRNPU on cancer progression were assessed through in vitro and in vivo experiments." (PMID 39773744, 2025). "Among the top downregulated 50 genes, there were other cancer relevant genes such as cell cycle associated (CCNF1, CCNB1, ZWINT), cancer signaling (STK32B, IGF1, FLT1) and splicing associated (HNRNPM, HNRNPU, SRSF1) genes, which are active areas to investigate further." (PMID 38200580, 2024). "This indicates that circUBE2G1 may exert oncogenic effects in a wider range of human cancers by binding with hnRNPU, highlighting its potential as a promising therapeutic target." (PMID 39664183, 2024). "HnRNPU is a multi-potent nuclear protein regulating transcriptional activation, RNA processing, or genome organization, and contributes to drug resistance and progression of cancer." (PMID 37993881, 2023). "Interestingly, the expression level of HNRNPU was higher in tumor tissues than in normal tissues in almost all cancer types." (PMID 35130920, 2022). "Our data highlight the synergetic effects of HNRNPU in RNA transcription and splicing in regulating cancer progression and suggest that HNRNPU may act as a potential molecular target in the treatment of TNBC." (PMID 36347834, 2022). "Interestingly, some NDD hnRNPs have already been implicated in cell division through cancer studies, including hnRNPD, hnRNPK, SYNCRIP, and hnRNPU." (PMID 33874999, 2021). "HNRNPs participated in cancer‐related pathways including protein secretion, mitotic spindle, G2/M checkpoint, DNA repair, IL6/JAK/STAT3 signal and coagulation, of which hnRNP genes of HNRNPF, HNRNPH2, HNRNPU and HNRNPUL1 are more likely to be implicated." (PMID 32915499, 2020). "Considering these results, TRA2B gene transcripts and hnRNPA1 or hnRNPU may be closely interacting regulators of the cell cycle or cell growth, which is a crucial phonotype of cancer cells." (PMID 31311954, 2019). "Moreover, the unique IHC staining of SYNCRIP and HNRNPU from BRCA could distinguish cancer tissues from normal tissues and help clinicians predict the clinical outcome." (PMID 33495416, 2021). "We recently demonstrated that RNA-binding domains of hnRNPU, RBM39 and hnRNPK inhibit the survival of a range of cancer cells." (PMID 38349913, 2024). "We previously demonstrated that RNA-binding domains of hnRNPK, hnRNPU, and RBM39 act as dominant-negatives and reduce cancer cell growth and viability." (PMID 38349913, 2024). "Our rescue studies indicated that circ-hnRNPU possessed tumor suppressive properties, at least in part, via repressing NONO activity, suggesting its potential as a therapeutic target against cancers." (PMID 37993881, 2023). "Heparanase (HPSE) is a cancer metastasis protein that is regulated by the hnRNPU/p300/EGR1/HPSE axis, promotes high expression of HPSE enhancer RNA, is an independent prognostic factor for poor prognosis in cancer patients." (PMID 37091789, 2023). "In our study, we first detected the expression of HNRNPU in 32 patients with BRCA cancer and found that its expression was considerably higher in cancer tissues than in adjacent tissues." (PMID 33495416, 2021). "hnRNPU and CTCF have been described to regulate target genes affecting cancer development." (PMID 35954396, 2022). "Meanwhile, circ-hnRNPU interacted with RRM1 domain of NONO to stimulate its cytoplasmic aggregation, which attenuated c-Myc transactivation, O-glycosylation, and N-glycosylation in cancer cells." (PMID 37993881, 2023). "Cross-linking RIP assay also indicated the abundance of circ-hnRNPU within NONO antibody-immunoprecipitated RNA in a variety of cancer cell lines, while steady transfection of circ-hnRNPU facilitated its interaction with NONO, resulting in decreased binding of NONO to hnRNPU mRNA." (PMID 37993881, 2023).